TTTY6 (testis expressed transcript, Y-linked 6)
Synonyms: TTY6; TTTY6A; LINC00127
Gene: Long non-coding RNA gene on chromosome Y (22,439,593 to 22,454,472, reverse strand). Ensembl gene ENSG00000131538.
Homologues: Paralogues in human: TTTY6B (100% identical).